CSNK2A1 (casein kinase 2 alpha 1)
Diseases named in the same sentence as CSNK2A1 in open-access papers (continued):
Sharing a sentence is not in itself a finding about the gene and the disease.
ovarian carcinoma (4 papers, 2016 to 2025). A malignant neoplasm originating from the surface ovarian epithelium. "The high expression levels of CSNK2A1 are associated with poor prognosis and increased tumorigenicity in ovarian cancer." (PMID 38038814, 2023). "The delivery of bioactive siRNAs targeting CSNK2A1 using fusogenic peptides has been shown to induce apoptosis in ovarian cancer cells in vitro and in vivo, suggesting a potential link between CSNK2A1 and mitochondrial function." (PMID 38038814, 2023). "Compared to non-targeting siRNAs, peptide DIV3W induced up to 94% suppression of CSNK2A1 mRNA and showed effective transport of bioactive siRNAs into ovarian cancer cells with high cellular uptake efficiency, which reduced cell migration and recolonization in vitro." (PMID 40230883, 2025). "Samec and co-authors developed and investigated three fusogenic peptide carriers, DIVA3, DIV3H, and DIV3W, composed of amphiphilic core repeats and a cationic poly(D-arginine tail, for delivering siRNA against casein kinase 2 alpha 1 (CSNK2A1) into ovarian cancer cells to reduce the aggressiveness." (PMID 37109432, 2023).
autism (3 papers, 2019 to 2025). Persistent deficits in social interaction and communication and interaction as well as a markedly restricted repertoire of activity and interest as well as repetitive patterns of behavior. "For example, Csnk2a1 displayed variable PA usage during neurodevelopment and across inhibitory neuron types in the adult brain; heterozygous mutations in CSNK2A1 are associated with autism and Okur–Chung neurodevelopmental syndrome." (PMID 37907328, 2023).
pancreatic cancer (3 papers, 2010 to 2025). "Thus, CSNK2A1, a gene associated with the phosphorylation and activation of key autophagy regulators, is overexpressed in gemcitabine-resistant pancreatic cancer cells." (PMID 40723396, 2025).
thyroid cancer (3 papers, 2022 to 2025). "This also renders CSNK2A1 a feasible new biomarker and future therapeutic target for thyroid cancer, paving the way for novel drug interventions in thyroid cancer." (PMID 36306106, 2023). "In the present study, we queried the binding of circNDST1 to CSNK2A1 via biotin-coupled probe pull-down and RIP assay and also confirmed CSNK2A1’s pro-carcinogenic role in thyroid cancer through a series of functional experiments." (PMID 36306106, 2023). "In the present study, we demonstrated that has_circ_0006943 promotes the development of thyroid cancer by binding to CSNK2A1, facilitating the binding of CSNK2A1 to Akt, and subsequently activating PI3A–Akt and EMT." (PMID 36306106, 2023). "For example, CSNK2A1 transcript levels were decreased in thyroid cancer cells yet corresponding CSNK2A1 protein levels were increased." (PMID 34773100, 2022). "Moreover, inhibition of CSNK2A1 in combination with BRAF inhibitors has a lethal synergistic effect by reducing AKT signaling in melanoma and thyroid cancer cells." (PMID 39820173, 2025).
type 2 diabetes mellitus (3 papers, 2020 to 2023). A type of diabetes mellitus that is characterized by insulin resistance or desensitization and increased blood glucose levels. "Individuals with type 2 diabetes mellitus showed a ~1.2-fold increase in CK2α gene (CSNK2A1) expression compared to nondiabetic individuals." (PMID 36613872, 2022). "The difference between our animal model (Obese Diabetes Mouse Model) and the Sacco animal model (Non-Obese Diabetes Model) resided in the fact that our model showed a possible correlation between CSNK2A1 and the obesity mechanism and regulation." (PMID 31929734, 2020).
atherosclerosis (2 papers, 2018 to 2021). A disease characterized by the build-up of fatty material and calcium deposition in the arterial wall resulting in partial or complete occlusion of the arterial lumen. "Several other module genes, including immediate neighbors of CAD candidate genes (e.g., CSNK2A1 and HTRA1) are also druggable and thus may be repurposed for modulating the effects of this module in the context of atherosclerosis prevention." (PMID 29467471, 2018).
breast tumor (2 papers, 2014 to 2016). "Approximately 30% and 20% of breast tumors have gains on CSNK2A1 (encoding CK2α) and CSNK2B (CK2β), respectively, while fewer gains are seen on CSNK2A2 (CK2α’)." (PMID 25153725, 2014).
clear cell renal cell carcinoma (2 papers, 2021 to 2023). "In clear cell renal cell carcinoma, higher expression of CSNK2A1 mRNA was associated with higher tumor stage, higher nuclear grade, presence of distant metastasis, and shorter OS." (PMID 34359939, 2021). "Similarly, the inhibition of CSNK2A1 with CX-4945 suppressed the proliferation of osteosarcoma cells and Caki-2 clear cell renal cell carcinoma cells." (PMID 34359939, 2021).
endometriosis (2 papers, 2023 to 2024). The growth of functional endometrial tissue in anatomic sites outside the uterine body. "Seven genes, namely, APPL1, CSNK2A1, ERG, KDM4A, SMARCC1, SUZ12 and TRIM25, were selected to establish the diagnostic model for endometriosis, and a nomogram was constructed based on them." (PMID 36860677, 2023). "Moreover, cyto-hub gene analysis revealed that CSNK2A1, CSNK2A2, TOP1, PRKACA, RBM39 (plasma), ALB, ACTB, GAPDH, FN1, APOA1 (serum), S100-A9, CXCL1, IL1RN, CSTA, S100-A8 (menstrual blood) and THBS1, ALB, CD44, ANXA2, and LUM (urine) were the top 5 proteins expressed in women with endometriosis." (PMID 39061077, 2024).
liver cancer (2 papers, 2020 to 2022). An epithelial or non-epithelial malignant neoplasm that arises from the liver. "In previous cancer studies, CSNK2A1 overexpression at the transcriptional and/or protein level was observed in breast and liver cancer samples 4,11,12." (PMID 31929734, 2020).
melanoma (2 papers, 2025). A malignant, usually aggressive tumor composed of atypical, neoplastic melanocytes. "Additionally, our examination showed that CDK2, GSK3B, CSNK2A1, and CDK1 were the significant kinases that target the greatest number of genes associated with metastatic-melanoma." (PMID 39820173, 2025). "Analysis of publicly available datasets (GEPIA) revealed that CSNK2A1 expression is elevated in melanoma tumors compared to non-tumor tissues." (PMID 41148289, 2025).
neuroblastoma (2 papers, 2007 to 2020). Neuroblastoma (NB) is the most common solid, extracranial childhood tumor. "In Cluster 1, transcripts are over-expressed in the mouse neuroblastoma cell lines in a tumor-restricted manner: Chgb, Dus31, 2310042G06Rik, Psma6 (proteasome subunit), Csnk2a1 (casein kinase), Mtrr (metabolic activation), and Hspa8 (heat shock protein)." (PMID 17397536, 2007).
pancreatic ductal adenocarcinoma (2 papers, 2022 to 2025). An infiltrating adenocarcinoma that arises from the epithelial cells of the pancreas. "Silmitasertib, a specific inhibitor of CSNK2A1, has been shown to restore gemcitabine sensitivity in pancreatic ductal adenocarcinoma, a cancer notoriously resistant to chemotherapy." (PMID 41377767, 2025).
schizophrenia (2 papers, 2017 to 2021). A major psychotic disorder characterized by abnormalities in the perception or expression of reality. "The other ASD proband shared a missense variant in CSNK2A1 with a schizophrenia proband." (PMID 34504065, 2021).
adrenal hypoplasia congenita (1 paper, 2025). "Genetic testing revealed a deletion in the CSNK2A1 gene, linked to Okur-Chung syndrome, along with a pathogenic NR0B1 variant, confirming adrenal hypoplasia congenita and hypogonadotropic hypogonadism." (PMID 40013223, 2025).
Autosomal dominant microcephaly (1 paper, 2020). "Among 141 protein coding genes within this deletion region, mutations only in SNRPB and CSNK2A1 have been reported to be associated with autosomal dominant microcephaly." (PMID 32863884, 2020).
Becker muscular dystrophy (1 paper, 2025). Becker muscular dystrophy (BMD) is a neuromuscular disease characterized by progressive muscle wasting and weakness due to degeneration of skeletal, smooth and cardiac muscle. "An SNP microarray revealed an interstitial duplication in exon 55 of DMD suggestive of Becker Muscular Dystrophy (BMD), but his degree of delays led to follow‐up exome sequencing revealing a pathogenic CSNK2A1 variant diagnostic for Okur–Chung Neurodevelopmental Syndrome." (PMID 39915227, 2025).
dementia (1 paper, 2025). Loss of intellectual abilities interfering with an individual's social and occupational functions. "Analyzing this dataset we found a specific increase in the expression of CSNK2a2, encoding for CK2α’, but not in CSNK2a1, encoding for CK2α, in patients with dementia compared to non-dementia controls in the PCx." (PMID 40799762, 2025).
eosinophilia (1 paper, 2024). "Some extremely rare fusion genes, such as CSNK2A1::PDGFRB, CBFB::MYH11, and NSD3::NUTM1, have been identified in patients with eosinophilia using RNA−seq techniques." (PMID 38992589, 2024).
gastric adenocarcinoma (1 paper, 2025). "We also noted the overexpression of CSNK2A1, a subtype of CK2, across multiple cancer cell lines, including SNU-16 (gastric adenocarcinoma) and HepG2 (hepatoblastoma)." (PMID 41035678, 2025).
HIV-1 infection (1 paper, 2018). The type species of lentivirus and the etiologic agent of acquired immunodeficiency syndrome (AIDS). "Inhibitors of CHEK2, CSNK2A1, and CDK2 did not significantly reduce CCR5-tropic HIV-1 infection but inhibited CXCR4-tropic HIV-1 at one or more concentrations." (PMID 29970186, 2018).
lymphoid tumors (1 paper, 2015). "GEP of the available study confirmed the trend of the immunohistochemical results, with high CSNK2A1, CSNK2A2 and CSNK2B mRNA levels in all the considered lymphoid tumors." (PMID 25788269, 2015).
lymphoma (1 paper, 2021). A malignant (clonal) proliferation of B- lymphocytes or T- lymphocytes which involves the lymph nodes, bone marrow and/or extranodal sites. "Protein kinase Cβ (PRKCB) plays a role in autophagy regulation, CREBBP inactivation promotes the development of HDAC3-dependent lymphomas, and abnormal expression of Casein kinase 2α1 (CSNK2A1) is linked to neurological diseases and cancer." (PMID 34211501, 2021).
meningioma (1 paper, 2020). A generally slow growing tumor attached to the dura mater. "Inhibiting the activity of ILK affected the levels of key proteins known to be key players in meningioma pathobiology namely EIF4G1, CSNK2A1, and several others." (PMID 32974197, 2020).
myeloid neoplasm (1 paper, 2021). Proliferation of myeloid cells originating from a primitive stem cell. "In myeloid neoplasms, the depletion of CSNK2A1 inhibited cell-cycle progression by elevating P27." (PMID 34359939, 2021).
Obesity (1 paper, 2020). Accumulation of substantial excess body fat. "Here, we showed strong evidence of the role of CSNK2A1 gene and protein expression in obesity and T2DM." (PMID 31929734, 2020). "Hence, further studies are required to explore CSNK2A1 protein levels in T2DM patients with obesity using a larger sample size." (PMID 31929734, 2020). "Therefore, all these evidences showed that the CSNK2A1 protein possibly played an important role in the obesity mechanism." (PMID 31929734, 2020). "However, further studies are required to understand the mechanisms of CSNK2A1 at the genomic and protein levels and to understand its association with pancreatic β-cell-mediated T2DM and obesity." (PMID 31929734, 2020). "Finally, ELISA was used to detect CSNK2A1 expression in T2DM patients with obesity." (PMID 31929734, 2020). "Altogether, our results indicate that CSNK2A1 plays an important role in T2DM and obesity regulation." (PMID 31929734, 2020). "Due to a lack of studies regarding CSNK2A1 expression at the genomic and protein levels in T2DM and obesity, we used the T2DM and obesity mouse model in this study to investigate the impact of CSNK2A1 on T2DM and obesity." (PMID 31929734, 2020). "Furthermore, we also presented time serial changes for obesity and diabetic parameters such as BMI, blood glucose, serum GPT enzyme activity, and CSNK2A1 gene and protein expression in this study." (PMID 31929734, 2020).
osteosarcoma (1 paper, 2021). A usually aggressive malignant bone-forming mesenchymal neoplasm, predominantly affecting adolescents and young adults. "In human osteosarcomas, especially in the patients who received adjuvant chemotherapy, the expression of CSNK2A1 was significantly associated with shorter survival." (PMID 34359939, 2021). "In this study, we demonstrated that the expression of CSNK2A1 was significantly associated with higher tumor stage and latent distant metastasis of osteosarcoma." (PMID 34359939, 2021). "Furthermore, in the sub-population of osteosarcoma patients who received postoperative chemotherapy, CSNK2A1 expression was significantly associated with shorter survival of patients." (PMID 34359939, 2021). "CSNK2A1-positivity predicted a 10.147-fold (95% CI; 2.320–44.385, p = 0.002) greater risk of death and a 12.179-fold (95% CI; 2.777–53.407, p < 0.001) greater risk of relapse or death in osteosarcoma patients." (PMID 34359939, 2021). "CSNK2A1-positivity predicted a 10.081-fold (95% CI; 2.307–44.054) greater risk of death and a 12.179-fold (95% CI; 2.777–53.407) greater risk of relapse or death in osteosarcoma patients." (PMID 34359939, 2021). "To evaluate the clinicopathological significance of the expression of CSNK2A1 and pSIRT6 in human osteosarcomas, we performed immunohistochemical staining for CSNK2A1 and pSIRT6." (PMID 34359939, 2021). "An interesting finding of this study is that the CSNK2A1-mediated phosphorylation of SIRT6 is important in the treatment efficacy of doxorubicin in osteosarcoma cells." (PMID 34359939, 2021). "In this study, we have shown that the CSNK2A1 inhibitor emodin synergistically potentiates the cytotoxic effect of doxorubicin in osteosarcoma cells." (PMID 34359939, 2021). "As we previously reported, CSNK2A1 phosphorylates SIRT6 on Ser338 among the four phosphorylation sites of SIRT6, and expression of CSNK2A1 was associated with phosphorylation of SIRT6 on Ser338 on U2OS and KHOS/NP osteosarcoma cells." (PMID 34359939, 2021). "Based on the role of CSNK2A1 in resistance to doxorubicin, we evaluated the effects of emodin, a CSNK2A1 inhibitor, on osteosarcoma cells." (PMID 34359939, 2021). "U2OS and KHOS/NP osteosarcoma cells with induced overexpression of CSNK2A1 were resistant to the cytotoxic effects of doxorubicin, and the knock-down of CSNK2A1 potentiated the cytotoxic effects of doxorubicin." (PMID 34359939, 2021). "Emodin, a CSNK2A1 inhibitor, potentiated the cytotoxic effects of doxorubicin in osteosarcoma cells." (PMID 34359939, 2021). "The proliferation of osteosarcoma cells that had a knock-down of CSNK2A1 was significantly lower compared with cells transfected with empty vector under treatment with doxorubicin." (PMID 34359939, 2021). "In our results, the knock-down of CSNK2A1 or the inhibition of CSNK2A1 with emodin sensitized osteosarcoma cells to doxorubicin." (PMID 34359939, 2021). "In the univariate analysis of 26 osteosarcoma patients who received adjuvant chemotherapy, the expression of CSNK2A1 (OS; p = 0.008, RFS; p = 0.003) and pSIRT6 (OS; p = 0.015, RFS; p = 0.008) were significantly associated with OS and RFS." (PMID 34359939, 2021). "Higher expression of CSNK2A1 and phosphorylated SIRT6 was associated with shorter survival in osteosarcoma patients." (PMID 34359939, 2021). "In this study, we present that the expression of CSNK2A1 and pSIRT6 might be used as important prognostic indicators of osteosarcoma patients, especially for patients who received postoperative chemotherapy." (PMID 34359939, 2021). "Therefore, a careful approach is needed to evaluate the possibility of CSNK2A1 as a potential therapeutic target of osteosarcoma based on the effect of CSNK2A1 on the proliferation of osteosarcoma cells." (PMID 34359939, 2021).
osteosarcoma (continued). "Positivity of pSIRT6 expression predicted an 18.649-fold (95% CI; 1.949–178.412) greater risk in OS analysis, and CSNK2A1 expression predicted a 10.374–fold (95% CI; 2.244–47.968) greater risk in RFS analysis in osteosarcoma patients who received adjuvant chemotherapy." (PMID 34359939, 2021). "Therefore, additional studies evaluating the effectiveness of various inhibitors of CSNK2A1 in osteosarcoma are needed." (PMID 34359939, 2021). "However, the effect of CSNK2A1 on the proliferation of osteosarcoma cells has been controversially reported." (PMID 34359939, 2021). "Therefore, blocking CSNK2A1 might be helpful in achieving therapeutic efficacy in osteosarcoma highly expressing CSNK2A1 and/or SIRT6." (PMID 34359939, 2021). "Therefore, when considering CSNK2A1-mediated resistance to doxorubicin as it relates to the DNA damage repair response, the use of PARP inhibitors also might be a potential therapeutic application in the treatment of poor prognostic osteosarcoma highly expressing CSNK2A1." (PMID 34359939, 2021). "Under doxorubicin treatment of U2OS and KHOS/NP osteosarcoma cells, the expression levels of cleaved PARP1, cleaved caspase 3, and BAX increased, and the expression of BCL2 decreased with the knock-down of CSNK2A1." (PMID 34359939, 2021). "We evaluated the expression of CSNK2A1 and phosphorylated SIRT6 in the 37 osteosarcoma patients and investigated the effects of CSNK2A1 and the phosphorylation of SIRT6 on Ser338 on resistance to the anti-cancer effects of doxorubicin." (PMID 34359939, 2021). "In contrast, the knock-down of CSNK2A1 sensitized U2OS and KHOS/NP osteosarcoma cells to doxorubicin in the CCK8 assay and colony-forming assay." (PMID 34359939, 2021). "In U2OS and KHOS/NP osteosarcoma cells, the overexpression of CSNK2A1 did not affect the proliferation of cells." (PMID 34359939, 2021). "A previous report showed that the knock-down or inhibition of CSNK2A1 inhibits the proliferation of osteosarcoma cells; however, in this study, the knock-down or overexpression of CSNK2A1 did not influence the proliferation of U2OS and KHOS/NP cells." (PMID 34359939, 2021). "The knock-down or overexpression of CSNK2A1 did not affect the proliferation of osteosarcoma cells without doxorubicin treatment." (PMID 34359939, 2021). "In addition, CSNK2A1-positivity predicted shorter OS and RFS in osteosarcoma patients." (PMID 34359939, 2021).
ovarian tumor (1 paper, 2015). "Given its over-expression in a majority of the ovarian tumor samples, its low SI value from the screen, and its catalytic nature, CSNK2A1 is a top candidate for potential drug screening/development and preclinical studies in combination with dasatinib." (PMID 26637171, 2015).
Pleural effusion (1 paper, 2022). The presence of an excessive amount of fluid in the pleural cavity. "For case 225 with supraventricular tachycardia, enlarged cisterna magna, ascites, and pleural effusion, a de novo nonsense variant was identified in the CSNK2A1 gene with very vague HPO “match” for cardiovascular system defects." (PMID 36307859, 2022).
sleeping sickness (1 paper, 2023). "HBA1, UBE2I, CSNK2A1, RRP12, and HSP90AB1 were highly enriched in African trypanosmiasis (sleeping sickness) than in the dengue viral infection pathway." (PMID 37498862, 2023).
Stillbirth (1 paper, 2025). Death of the fetus in utero after at least 22 weeks of gestation. "Our study reported a stillbirth case with intracranial anomalies and cardiovascular malformations, where whole-genome sequencing (WGS) identified a novel CSNK2A1 frameshift variant." (PMID 41216289, 2025). "In our research, a novel mutation c.1020_1021delAG (p.Gly342Glnfs*57) in the locus on exon 13 of the CSNK2A1 gene was identified by WGS in a stillbirth case." (PMID 41216289, 2025).